CERS1 (ceramide synthase 1)
Diseases named in the same sentence as CERS1 in open-access papers (continued):
Sharing a sentence is not in itself a finding about the gene and the disease.
tumor (17 papers, 2013 to 2024). "To explore the tumor characteristics in the subcutaneous xenograft model, we conducted IHC staining for CERS1 and the metastasis-associated marker MMP-9 in xenograft tissues." (PMID 37046655, 2023). "C18-ceramide production by CerS1 is inhibited in HNSCC through transcriptional repression via histone deacetylase 1 (HDAC1)-dependent inhibition of Sp1 at the promoter, and post-transcriptionally by miR574-5p that induces translation of a CerS1 isoform 2 splice variant common in HNSCC tumor tissues." (PMID 34069611, 2021). "CERS1 reportedly promotes the killing effect of cisplatin on tumor cells by activating the P38 MAPK signaling pathway." (PMID 37046655, 2023). "In the subcutaneous xenograft model, tumor size in the CERS1 overexpression group was smaller than that of the control group (p < 0.001), while the CERS1 knockdown group showed the opposite result (p < 0.001)." (PMID 37046655, 2023). "Given that LCA, an established tumour promoter, has been implicated in CRC metastasis and is primarily presented within the colon, we examined the expression of Cers1, Cers2, Cers5, and CERK in LCA-stimulated human intestinal epithelial cells." (PMID 37298127, 2023). "In HNSCC cells, CERS1 overexpression or C18-ceramide treatment suppresses tumor growth, but CERS6 downregulation produces ER stress leading to apoptosis of cells." (PMID 29262618, 2017). "Ceramide species differentially regulate tumor growth and invasion, namely ceramide synthase-1 (CerS1, also known as longevity assurance gene 1, LASS1) and ceramide synthase-6 (CerS6 or LASS6)." (PMID 24970177, 2013). "For instance, CerS1 produces ceramides(18:0), which inhibit tumor growth, while CerS5 and CerS6 generate ceramides (16:0),which are associated with anti-apoptotic effects in headand neck squamous cell carcinoma.The CerS1-specific inhibitor P053 reduces ceramide (18:0)levels in HEK 293 cells." (PMID 39944803, 2024). "However, in their in vivo model, CerS6/C16-ceramide protected ER stress and tumour growth was enhanced in comparison to CerS1/C18-ceramide." (PMID 38720356, 2024). "Further, CERS1 expression substantially suppressed BM tumor formation in vivo." (PMID 37046655, 2023). "However, the average tumor lesion size in the Cers1 + /+ group was smaller at (3.5 ± 5.6) mm2 (P = 0.033)." (PMID 33753723, 2021). "A targeting drug delivery system might be a way to increase CERS1 specifically in tumor cells or apply C18-ceramide to tumor cells in vivo." (PMID 29262618, 2017). "Furthermore, CERS1 and C18-ceramide have emerged as tumor suppressors in preclinical and clinical studies." (PMID 29262618, 2017). "In addition, patients with lower expression of CERS1 in tumor tissues had a worse prognosis." (PMID 33753723, 2021). "For example, CerS1/C18 ceramides suppress HNSCC xenograft tumor growth, and CerS6/C16 ceramides induce HNSCC tumor proliferation in SCID mice." (PMID 31676768, 2019). "Thirdly, to determine CerS1 and GRP78 expression levels in excised tumours." (PMID 38720356, 2024). "It was reported that CerS1 and C18-ceramide induced LC3B-phosphotidylethanolamine lipidation, forming LC3B-II, targeting autophagolysosomes to mitochondria and leading to lethal mitophagy and tumor suppression." (PMID 29262618, 2017). "Data showed that I2PP2A/SET is overexpressed in 70% (7/10, n = 10) of these tumours, whereas C18-ceramide and CerS1 mRNA levels are decreased (∼50%) in the majority of tumours (8/10, n = 10) compared to non-cancerous lung tissues (respectively)." (PMID 23180565, 2013). "CerS1 was not upregulated in the tumour sections upon immunohistochemistry staining which may indicate that CerS1 induced cytotoxicity is induced by CBD." (PMID 38720356, 2024).
cancer (11 papers, 2015 to 2025). A tumor composed of atypical neoplastic, often pleomorphic cells that invade other tissues. "Considering these findings, investigation of CerS1 expression levels in other cancer models have shown both high and low levels associated with poor prognosis." (PMID 38720356, 2024). "Bile acid, namely LCA, activated cancer-promoting genes including Cers1, Cers2, Cers5, and CERK in the cancerous HT-29 cell line in a miR125b-dependent way." (PMID 37298127, 2023). "Understanding the way ceramide and CERS1 sensitize or desensitize cancer is essential for developing new cancer therapies for patients." (PMID 37614280, 2023). "The association between CERS1 and the PI3K/AKT/mTOR signaling pathway in our study is a newly found and important supplement to the mechanism of CERS1 in malignant tumors." (PMID 37046655, 2023). "CerS1-generated Cer 18:0 influences cancer cell survival, apoptosis, and mitophagy." (PMID 40075508, 2025). "Furthermore, CERS1 was generally downregulated in various cancer cells, according to the CCLE database." (PMID 37046655, 2023). "In prior cancer research, CerS1, but not CerS4, increased cellular sensitivity to cisplatin, a chemotherapeutic drug, with enhanced cell death." (PMID 41217173, 2025).
infection (1 paper, 2017). The state of being infected such as from the introduction of a foreign agent such as serum, vaccine, antigenic substance or organism. "We thus analysed the role of phagocytic cells by selective depletion of this cell type via Smed-CerS1 (RNAi) treatment 15 days after primo-infection." (PMID 28456423, 2017).
muscular disorders (1 paper, 2020). "These few cases are consistent with the notion that CerS1 and CerS5 may also be linked to muscular disorders in chronic diseases." (PMID 31692231, 2020).
myopathies (1 paper, 2020). "Genetic deficiencies of CerS1 and CerS5 showed reduced caliber sizes of type 1 and type 2 muscle fibers, ragged red fibers as histological signs of myopathy, and reduced strength." (PMID 31692231, 2020).
neurological disease (1 paper, 2017).
CERS1 also shares sentences with these, for which no sentence is quoted: Ataxia (2 papers); head and neck cancer (2); neurodegenerative disease (2); sarcopenia (2); Aphthous Stomatitis (1); Emery-Dreifuss muscular dystrophy (1); facioscapulohumeral muscular dystrophy (1); fatty liver (1); Glucose intolerance (1); hepatopathy (1); influenza (1); liver cancer (1); movement disorder (1); muscle disorders (1); muscular atrophy (1); myoclonus epilepsy (1); Oral leukoplakia (1); ovarian carcinoma (1); pancreatic cancer (1); peripheral neuropathy (1); Progressive myoclonic epilepsy (1); squamous cell carcinoma (1).